TNF (tumor necrosis factor)
Diseases named in the same sentence as TNF in open-access papers (continued):
Sharing a sentence is not in itself a finding about the gene and the disease.
Hepatic steatosis (continued). "In ALD cases, hepatic steatosis can lead to concomitant changes in the gene expression levels of proinflammatory factors such as TNF-α, IL-6, and IL-1β." (PMID 38999886, 2024). "The contribution of inflammation to the development of MASLD is supported by the resistance to liver steatosis in TNF-α–/– mice and mice treated with a TNF-α receptor antagonist." (PMID 39529929, 2024). "Studies conducted on animals also demonstrate that fatty liver disease and IR can be improved by blocking TNF-α activity." (PMID 38535313, 2024). "Given that TNFα leads to RIPK3 activation and necroptosis induction, which increases inflammation and TNFα levels, ATF3-dependent induction of RIPK3 in severe hepatic steatosis can cause a vicious cycle of necroptosis and inflammation." (PMID 36690638, 2023). "As demonstrated in previous studies, IL-6 and TNF-α are significant cytokines in the development of hepatic steatosis." (PMID 38116565, 2023). "The contribution of TNF-α to the development of NAFLD is supported by the resistance to liver steatosis in TNF-α−/− mice and mice treated with a TNF-α receptor antagonist." (PMID 38075211, 2023). "GP also alleviates hepatic steatosis and mitochondrial damage and downregulates the expression of inflammation-related factors, including tumor necrosis factor-alpha (TNF-α) and nuclear factor kappa B (NF-κB) in NAFLD model mice." (PMID 37065701, 2023). "IL-1β is directly involved in IL-1β/TNF-induced hepatocyte necrosis, promoting hepatic steatosis, with positive feedback amplification of inflammation-induced IL-1β and TNF-α." (PMID 38145041, 2023). "Mitoquinone and ASA significantly reduced liver steatosis and inflammation by decreasing the expression of TNFα, IL-6, Serpinb3, and cyclooxygenase 1 and 2 and restoring the anti-inflammatory IL-10." (PMID 37107346, 2023). "Abnormal increase of FFAs level in blood will directly stimulate FFAs uptake in liver, which stimulated TNF-α expression and lead to accumulation of TG and liver steatosis." (PMID 37533083, 2023). "Saroglitazar treatment significantly reduced the liver injury markers (serum ALT and AST), reversed hepatic steatosis and decreased the levels of pro-inflammatory cytokines like TNF-α in liver." (PMID 36650455, 2023). "Another flavone, Baicalin, was shown to have a protective effect against liver steatosis (fatty liver disease) through the reduction of levels of a pro-inflammatory cytokine: TNF- α." (PMID 37252233, 2023). "It has been demonstrated that a high-fat diet induces hepatic tumor necrosis factor-a (TNF-a) and interleukin (IL)-6 expression, whereas their inhibition prevents hepatic steatosis and NAFLD progression." (PMID 35739957, 2022). "TNF-α also inhibits β-oxidation by inhibiting peroxisomal fatty acyl-CoA oxidase, which promotes hepatic steatosis." (PMID 36497051, 2022). "It not only directly induces hepatic steatosis but also indirectly promotes it by increasing the secretion of proinflammatory cytokines such as interleukin (IL)-1, IL-6, and tumor necrosis factor-alpha (TNF-α)." (PMID 36364718, 2022). "There is a consensus that oxidative stress and inflammatory mediators such as TNF-α and IL-6, which are hallmarks of liver steatosis, can alter the function of nuclear receptors (NRs) in NAFLD." (PMID 35625421, 2022). "Conversely, TNF-α promotes the hepatic expression of SREBP1c, a major regulatory transcription factor in hepatic lipogenesis and the development of hepatic steatosis in humans." (PMID 36082001, 2022). "The hepatic steatosis was induced on-chip by tumor necrosis factor-α, which increases the permeability of gut epithelium and, as a result, increases the level of lipid permeability to the liver tissue, leading to hepatic steatosis." (PMID 35447710, 2022). "After feeding the HF diet for 8 weeks, hepatic steatosis and inflammatory cell infiltration as well as the higher TNF-α level were observed." (PMID 35270077, 2022).
Hepatic steatosis (continued). "Hepatic steatosis can then induce or accelerate the disruption of the gastrointestinal tract via pro-inflammatory cytokines (e.g., TNF-α, IL-6, and IL-8) that promote tumor formation in the colon." (PMID 36548355, 2022). "The TNF signaling pathway has been proven to not only be the key regulator of liver inflammation but also to have a significant influence on liver steatosis." (PMID 36172180, 2022). "For example, TNF-α, which stimulates liver steatosis, increases serum triglyceride levels, hence supplying energy to the tissue." (PMID 35991915, 2022). "Anti-inflammatory drugs, such as vitamin E and anti-TNF-α antibodies, reduced the levels of pro-inflammatory cytokines and improved insulin resistance and fatty liver disease." (PMID 36077452, 2022). "TNF-α and IL-6 induce adipogenesis and increase the production and secretion of TGs, which promote the development of hyperlipidemia and fatty liver disease." (PMID 35967316, 2022). "This will then result in the production of large amounts of proinflammatory cytokines, including interleukin (IL)-1β and tumor necrosis factor (TNF) α which in turn accelerate hepatic steatosis, inflammation, and fibrosis." (PMID 34830072, 2021). "In the process of hepatic steatosis, the production of proinflammatory mediators such as TNF‐α and IL‐6 contributes to the activation Kupffer cells." (PMID 33720453, 2021). "Patients with steatosis show the highest TNF‐α and IL‐6 levels, indicating that there is an inflammation during hepatic steatosis." (PMID 34760237, 2021). "Given the relationship between the severity of hepatic steatosis and cytokines, the expression of TNF-α was more concomitant with the severity of hepatic steatosis than that of IL-6." (PMID 33388967, 2021). "The M1 phenotype works to promote pro-inflammatory cytokines like TNF-α and IL-1β which contribute to the pathogenesis of hepatic steatosis." (PMID 34557866, 2021). "Dietary intake of onion was revealed to lower hepatic steatosis, inflammation, and hepatic TNF-α expression in high-fat, high-sugar diet-fed rats." (PMID 34368207, 2021). "By stimulating Kupffer cells to activate the TLR4 signaling pathway, LPS induces the secretion of TNF-α, IL-1, IL-6, IL-12, and IL-18 in Kupffer cells, thereby triggering hepatic steatosis, IR, and hepatocyte apoptosis, among others." (PMID 34966296, 2021). "After activation, hepatic macrophages release proinflammatory interleukin-1β and TNF-α, which facilitate the inflammatory transition from simple fatty liver to steatohepatitis." (PMID 34916874, 2021). "TNF-α correlated significantly with hepatic steatosis (r = 0.415, P < 0.05), lobular inflammation (r = 0.441, P < 0.05), ballooning (r = 0.557, P < 0.01), steatohepatitis (r = 0.466, P < 0.05) and fibrosis septa around the central vein (r = 0.487, P < 0.05)." (PMID 34305638, 2021). "The strong correlation observed between FRAP and IL10/TNF ratio in LPHs-treated mice re-enforces the interplay between the oxidative stress and inflammation in the context of fatty liver disease." (PMID 34439470, 2021). "Under FFA stimulation or an HFD-induced microenvironment of fatty liver disease, activated KCs release more TNF-α and IFN-γ." (PMID 34956171, 2021). "In patients with fatty liver disease, TNF-α and IL-8 released from myeloid-derived immune cells, including KCs, DCs, and neutrophils, are positively correlated with the severity of fatty liver disease." (PMID 34956171, 2021). "The interleukin (IL)-1-family cytokine members and tumor necrosis factor alpha (TNFα) are key inflammatory cytokines involved in fatty liver diseases." (PMID 34038475, 2021). "Elevated TNF-α levels have been found in cows with fatty liver, and administration of recombinant bovine TNF-α (rbTNFα) for 7 days leads to triglyceride accumulation and hepatocyte inflammation with decreased gluconeogenesis." (PMID 35050141, 2021).
Hepatic steatosis (continued). "During the progression of liver damage in fatty liver disease, the accumulation of fat in hepatocytes triggers oxidative stress, which induces the production and release of TNF-α and TGF-β by Kupffer cells." (PMID 34440206, 2021). "Hepatic macrophages participate in the development of fatty liver disease by secreting multiple pro-inflammatory cytokines, including IL-1β, IL-6, and TNF-α." (PMID 34956171, 2021). "Increased numbers of myeloid cells and induction of TLRs and TLR-dependent pathways (e.g., MyD88, iNOS, and TNF-α) were found to present in liver with fructose-induced hepatic steatosis." (PMID 32121028, 2020). "Hepatic induction of HO-1 reduces not only hepatic steatosis but also decreases inflammatory factors such as suppressor of cytokine signaling-1, interleukin-6, and tumor necrosis factor-alpha." (PMID 33327438, 2020). "But in Sirt1+/− mice on HFD, body weight, fat content and hepatic steatosis are increased, adipose tissue macrophage infiltration and expression of inflammatory genes, indicated by the expression of F4/80, TNF-α, IL-1, and IL-6, are enhanced in epididymal fat." (PMID 33390968, 2020). "TNF is a key promoter of other inflammatory cytokines and molecules related with hepatic steatosis and fibrosis." (PMID 33363197, 2020). "Excessive alcohol consumption elevates the TNF-α level, which results in alcohol-related liver diseases, such as fatty liver, hepatitis, cirrhosis and cancer." (PMID 32151025, 2020). "TNF-α also suppresses β-oxidation through inhibition of peroxisomal fatty acyl-CoA oxidase 53 to promote hepatic steatosis." (PMID 32863955, 2020). "Numerous factors such as leptin, TNF-α, and IL-6 are involved in the initiation and progression of hepatic steatosis and related metabolic dysfunction." (PMID 32528465, 2020). "Green tea polyphenol lowered the content of TNF-α in the liver and adipose tissues and improved hepatic steatosis by regulating the expression of SREBP-1c, FAS, and SCD1." (PMID 33312340, 2020). "Contradicting the two-hit model, it was recently shown that interleukin(IL)-6 or TNF, originating from adipose tissue, can trigger liver inflammation in parallel with or even before hepatic steatosis." (PMID 33050035, 2020). "Mechanistic studies found that herbal formula such as shenling baizhu powder alleviated hepatic steatosis and repaired colon mucosa via decreasing the expression level of endotoxin and inflammatory mediators (TNF-α, IL-1β) via the TLR4 pathway." (PMID 32477116, 2020). "Flaxseed oil rich in ALA intervention apparently decreased the serum level of inflammatory cytokines (IL-6, IL-1β, MCP-1, and TNF-α) and attenuated hepatic steatosis by regulating ER stress." (PMID 33273997, 2019). "TNF knockout reduced the progression of hepatic steatosis and fibrosis by downregulation of MCP-1, TGF-1β, Col1a1, and TIMP-1 in transgenic mice." (PMID 31001563, 2019). "Previous study has demonstrated that treatment with antibiotics (e.g., polymyxin B) targeting gram-negative bacteria efficiently reduced tumor necrosis factor (TNF) production and plasma LPS levels, leading to the reversal of hepatic steatosis." (PMID 31349604, 2019). "Hepatic steatosis and serum level of liver enzymes, and tumor necrosis-α (TNF-α) significantly reduced in both groups (p < 0.05)." (PMID 31345163, 2019). "Both in vivo and in vitro studies have reported that TNFα and IL-6 can exacerbate hepatic steatosis." (PMID 29684027, 2018). "In our study, chronic vitamin D treatment decrease hepatic steatosis by suppressing the levels of TNFα, NFκB and IL-6 in NASH rat livers." (PMID 29684027, 2018). "By month 2, the body weight and epididymal fat weight started increasing, which was associated with increased serum levels of FFA, cholesterol, and TNF-alpha, as well as development of fatty liver." (PMID 30515333, 2018). "There is a characteristic cytokine pattern in liver steatosis such as the increase in TNF-α and IL-6." (PMID 30158441, 2018).
Hepatic steatosis (continued). "Upregulation of SREBP-1 activity in fatty liver can result in the production of tumor necrosis factor-α (TNF-α), but TNF-α can also contribute to the development of alcoholic fatty liver by upregulating SREBP activity." (PMID 29091708, 2017). "Several studies have suggested that TNF-α mediates the early stages of fatty liver disease as well as the transition to more advanced stages of liver damage." (PMID 29091708, 2017). "Deletions of C536 and C1q39 also alleviate hepatic steatosis and suppress the expression of inflammatory factors (TNFα and IL6) induced by alcohol." (PMID 27550859, 2016). "In this study, the group with fatty liver showed a significantly higher level of serum tumor necrosis factor (TNF)-α than the control group did, which correlated with the pathological severity of the hepatic lesions." (PMID 27455313, 2016). "In the same model as ours, linagliptin alleviates hepatic steatosis and inflammation by reducing macrophages infiltration and lobular inflammation, as well as expression of TNF-α and IL-6." (PMID 27462372, 2016). "In this study, KMUP-1 increased IL-10 and decreased MMP-9 significantly, little affected TNFα, indicating its anti-inflammatory properties in hepatic steatosis." (PMID 27548140, 2016). "An accumulating number of high-quality preclinical studies have confirmed its efficacy for reducing hepatic lipogenesis, resulting in inactivation of liver X receptor α (LXRα) and inhibition of TNF-α, thereby preventing hepatic steatosis." (PMID 27560482, 2016). "Here we demonstrate that Arg-II−/− mice reveal decreased hepatic steatosis, macrophage infiltration, TNF-α and IL-6 as compared to the wild type (WT) littermates fed high fat diet (HFD)." (PMID 26846206, 2016). "It is reported that TNF-α is the most critical inflammatory cytokine in the progression of fatty liver." (PMID 26610473, 2015). "Adiponectin administration, in both alcoholic and nonalcoholic fatty liver in mice, was found to suppress hepatic production and the circulating levels of tumor necrosis factor-α and ameliorates hepatic steatosis." (PMID 26640716, 2015). "TNF-α play an important role in hepatic steatosis, HFD-induced increase in hepatic TNF-α production was significantly suppressed by cholesterol-lowering probiotics combined with AC treatment (P<0.05)." (PMID 26375281, 2015). "Kupffer cells, activated by liver injury, have been shown to be essential for the development of diet-induced hepatic steatosis in rats, as they alter metabolic pathways in hepatocytes through TNFα secretion." (PMID 26047317, 2015). "Especially, TNF-α mediates the early stage of fatty liver disease as well as the transition to a more advanced stage of liver disease, and stimulates the release of cytokines such as IL-4 and IL-6." (PMID 26375281, 2015). "The reduction of adiponectin seems to have a major impact on the development of hepatic steatosis and NASH caused by its direct antagonistic effect on TNFα, one of the most important cytokines in mediating inflammation." (PMID 24897026, 2014). "Nevertheless, inhibition of TNFα via TNFR1 or of IL-6 through antibodies or blocking of IKKβ activity protects against hepatic steatosis." (PMID 24897026, 2014). "Clinical studies show NASH patients with phenomenally high TNF-α expression than those with other fatty liver disease." (PMID 25520925, 2014). "In rodent studies, TNFα was shown to be dysfunctionally released when animals exhibited hepatic steatosis, and this TNFα contributed to NASH severity." (PMID 23720231, 2013). "The inhibition of TNF-α improved NAFLD in HFD-fed ob/ob mice, while TNF-α receptor-deficient mice protected against hepatic steatosis." (PMID 23690838, 2013). "In the current study, exacerbated hepatic steatosis in MOT group was evidenced by an elevated hepatic immunophenotype which included upregulated TNF-α and IL-1β expression." (PMID 24146946, 2013).
Hepatic steatosis (continued). "The role of some adipocytokines, such as leptin and TNF-α in hepatic steatosis has also been increasingly studied." (PMID 21961071, 2011). "IR promotes fibrosis progression in the liver of patients with HCV through development of hepatic steatosis, hyperleptinemia, increased TNF production and reduced expression of peroxisome proliferator activated receptors (PPAR ץ receptors)." (PMID 22044490, 2011). "TNF-alpha not only mediates the early stages of fatty liver disease, but also the transition to advanced stages of liver damage." (PMID 20653983, 2010). "This suitably agrees with the fact that TNFα is very significant in the pathogenesis of fatty liver diseases that accompanies a host of metabolic disorders." (PMID 20140224, 2010). "In summary, our study shows that resveratrol decreases liver steatosis in rats and that its effect is mediated, at least partly, by TNF-α and antioxidant activities." (PMID 18782455, 2008). "The MAS score and levels of pro-inflammatory markers, including IL-6, IL-1β, and TNF-α, were significantly decreased following EA administration, demonstrating the compound's efficacy in attenuating hepatic steatosis and inflammation in a dose-responsive manner." (PMID 41530836, 2026). "Cytokines, particularly interleukin (IL)-6, IL-18, and tumor necrosis factor (TNF)-α, could promote intra-hepatic lipid peroxidation and peripheral lipolysis, contributing to hepatic steatosis." (PMID 40700400, 2025). "Indeed, deletion of Apoa5 in hamsters led to hepatic steatosis even on a chow diet, and Apoa5 knockdown in mice resulted in increased cytokine markers of systemic inflammation, including IL-10, IL-6, and TNF-α." (PMID 41043689, 2025). "Indeed, many studies highlight an important role of TNF in hepatic steatosis and lipotoxicity as blocking TNF signaling via TNFR1 significantly improved fat accumulation in mouse models of metabolic dysfunction-associated steatotic liver disease." (PMID 41132685, 2025). "While prior work has also implicated inflammasome activation in the development or hepatic steatosis, our findings do not suggest systemic measures of IL-6, IL-18, TNF-α are associated with greater hepatic fat deposition." (PMID 40700400, 2025). "We evaluated IL-6, IL-18, and TNF-a because these might promote intra-hepatic lipid peroxidation and peripheral lipolysis, which could contribute to development of hepatic steatosis." (PMID 40700400, 2025). "In vitro, fructose treatment attenuated the expression of key pro-inflammatory cytokines (TNF-α and IL-6) in hepatocytes, which might contribute to the relatively low-grade inflammation in goose fatty liver despite severe steatosis." (PMID 41378259, 2025). "Chitin oligosaccharides can increase SCFAs content, reduce serum LPS, improve blood lipid profiles and liver steatosis, decrease the levels of inflammatory factors such as IL-1β, IL-6, and TNF-α to alleviate inflammation, and promote mRNA expression of TJPs to enhance the integrity of the IMB." (PMID 40862134, 2025). "Furthermore, inflammatory cytokines (e.g., TNF-α and IL-6) impair insulin signaling, leading to insulin resistance, which stimulates liver fat synthesis and inhibits fat degradation, exacerbating liver steatosis." (PMID 40746546, 2025). "Chronic systemic inflammation, characteristic of IBD, may contribute to hepatic lipid accumulation through inflammatory cytokines such as tumor necrosis factor-alpha and interleukin-6, which interfere with insulin signaling and promote hepatic steatosis." (PMID 41416325, 2025). "First, hepatic steatosis induces chronic low-grade inflammation, characterized by elevated inflammatory cytokines (e.g., IL-6, TNF-α) and C-reactive protein (CRP), which can affect the central nervous system by altering neurotransmitter metabolism and impairing mood regulation." (PMID 41011102, 2025).